CGAS (cyclic GMP-AMP synthase)
Diseases named in the same sentence as CGAS in open-access papers (continued):
Sharing a sentence is not in itself a finding about the gene and the disease.
tumor (continued). "Therefore, this work developed a novel biomaterial for improving the immune stimulation effect of EBRT and RNT, and discovered some differences in cGAS-STING pathway activation between EBRT and RNT, providing some reference and strategic design for the implementation of clinical tumor RT." (PMID 38831378, 2024). "As a cytoplasmic DNA receptor, cGAS can be activated by DNA and/or Mn2+ to synthesize the second messenger 2′3′-cGAMP using ATP and GTP, which further activates STING and induces the production of type I interferons and other cytokines, thereby eliciting tumor immune responses." (PMID 39170694, 2024). "The in vitro and in vivo studies demonstrate that the MHN NGs can activate the cascade tumor pyroptosis and cGAS‐STING immunotherapy under the US treatment through the synergistic effects of generated NO and released Mn2+, resulting in the effective inhibition of tumor growth." (PMID 37400368, 2023). "In addition, cGAS depletion in M38 tumor-bearing mice abolishes the IR-induced infiltration of CD8+T, CD8+GZMB + T-cells leading to reduced antitumor efficacy, thus corroborating the role of cGAS for the combination efficacy." (PMID 37388241, 2023). "Recent study demonstrate that the cyclic GMP-AMP synthase (cGAS)-stimulator of interferon genes (STING) pathway plays a key role in regulating immune and inflammatory response, and may serve as an important mechanism to regulate tumor progression." (PMID 36879291, 2023). "The M-M NPs could activate cGAS-STING pathway and promote the maturation of antigen-presenting cells to initiate systemic anti-tumor immune response such as increasing the production of tumor-specific T cells and more pro-inflammatory cytokines and chemokines." (PMID 38298540, 2023). "Due to the central role of cGAS-cGAMP in sensing cytoplasmic DNA, we hypothesized that infection of cancer cells by an oncolytic VACV including a deleted B2R gene could result in more immunogenicity and boost innate immunity within the tumor." (PMID 37016144, 2023). "The in vitro and in vivo results confirmed that ZnFe2O4‐PTX@CCM elevated the cGAS/STING activity, promoted dendritic cell maturation, increased cytotoxic T lymphocyte and natural killer cells infiltration, eventually inhibiting the tumour progress and postoperative recurrence." (PMID 38264691, 2023). "The DNA fragment carried by tumor‐derived extracellular vesicles activates the cGAS‐STING signaling pathway to induce DC cells to produce IFN‐I, which in turn promotes the activation and maturation of DC cells, enhances their antigen presentation, and promotes anti‐tumor immune response." (PMID 35861052, 2023). "The cyclic guanosine monophosphate‐adenosine monophosphate synthase (cGAS)/stimulator of interferon genes (STING) signalling pathway has been a promising target for anticancer immunity, but rationally activating and enhancing this pathway in tumour cells is critical." (PMID 38264691, 2023). "Thus, we explored whether the exposure of cytoplasmic mtDNA could stimulate immunity through cGAS-STING pathway activation, and revealed the immunoadjuvant effect of tumor microenvironment-driven gas therapy." (PMID 37221157, 2023). "In addition to cellular damage, viral or bacterial invasion, extracellular self-nucleic acid (tumor-secreted DNA)-induced cGAS / STING signaling, or binding of other non-nucleic acids (DAMPs) via TLRs all drive Type I IFN production." (PMID 37090639, 2023). "Taken together, based on the results of our IHC analyses, decreased expression of STING in tumor cells might be involved in the low infiltration of both CD8+ and CD4+ T cells, and low expression of cGAS in tumor cells might be involved in the low infiltration of CD8+ T cells in pMMR/MSS CRC." (PMID 37345163, 2023).
tumor (continued). "The HER2-AKT oncogenic pathway inhibits cGAS-STING pathway-mediated DNA immune recognition by suppressing STING-TBK1 interaction, as well as TBK1 K63-type ubiquitination, thereby inhibiting type I IFN production, cellular senescence, and apoptosis in tumor cells." (PMID 37153627, 2023). "Similarly, pharmacological inhibition of polyadenosine diphosphate-ribose polymerase (PARP) and checkpoint kinase 1 (CHK1) in small-cell lung cancer results in the inhibition of the DDR pathway and activates the cGAS-STING pathway, evoking an anti-tumour immune response." (PMID 37448962, 2023). "Importantly, our data demonstrate that medicinal plant-derive mtDNA, enclosed in the nanovesicles and preferentially taken by TAMs, induces the cGAS-STING pathway to promote the transition of macrophages from the immune-tolerant to proinflammatory phenotypes, and thereby controls tumor progression." (PMID 36879291, 2023). "cGAS, the enzyme responsible for generation of endogenous STING ligands, was indeed shown to mediate dendritic cell sensing of irradiated tumor cells, suggesting that stereotactic radiation techniques may depend on host STING and the downstream type I IFN driven response." (PMID 37426669, 2023). "However, emerging evidence suggest that there are myriad cellular processes beyond cytosolic immunity in which cGAS and STING are active participants, which may explain why pathway activity is maintained in some tumour contexts." (PMID 36876871, 2023). "Thus, the targeted degradation of STING can not only affect the integrity of the cGAS-STING signaling but also dysregulate the positive feedback system in which cisplatin and STING promote each other, disrupting the tumor-killing effect of cisplatin with STING involvement." (PMID 37569723, 2023). "The frequency of cGAS+/STING+ cases was reduced in the advanced stages of pMMR/MSS CRC, and histone methylation might be involved in the down-regulation of STING expression in tumor cells." (PMID 37345163, 2023). "Moreover, the convergence of multiple of these processes, including DNA damage responses, cell cycle control, senescence, autophagy and cell death, on genome stability regulation underscores the relevance of cell-intrinsic cGAS and STING functions to CIN tumours in particular." (PMID 36876871, 2023). "When bound to dsDNA, the nucleotidyl transferase activity of cGAS is stimulated, triggering a signaling cascade reaction involving STING, which results in the production of type I IFN to initiate the innate immune response and generate the subsequent adaptive anti-tumor immune response." (PMID 36798129, 2023). "Based on this, a protein-based cGAS-STING nanoagonist (bovine serum albumin (BSA)/ferritin-based nanoagonist incorporating manganese (II) ions and β-lapachone) was discovered to enhance tumor-specific T-cell-mediated immune responses against poorly immunogenic solid tumors in vivo." (PMID 37354378, 2023). "The released Mn2+ could further activate cGAS-STING signaling and promote the maturation of antigen-presenting cells to elicit systemic anti-tumor immune responses, such as the augmentation of tumor-specific T cells and pro-inflammatory cytokines/chemokines production." (PMID 37153576, 2023). "The latest research has indicated that combining cGAS-STING pathway-targeted agents with other immunotherapeutic approaches, such as immune checkpoint inhibitors, may result in enhanced anti-tumour efficacy, further highlighting the potential of this pathway in personalized cancer therapies." (PMID 37667220, 2023). "As such, cGAS–STING-driven autophagy may, to an extent, act on a cell-intrinsic level to ensure unstable genome homeostasis by enabling cell survival at low-level CIN and driving the elimination of tumour cells in circumstances of high or acutely-driven CIN." (PMID 36876871, 2023).
tumor (continued). "In accordance, many TLRs agonists (imiquimod for TLR7 and CpG for TLR9) or cGAS-STING triggers were employed to activate anti-viral interferon-mediated immune responses with final aim to polarise myeloid cells towards an anti-tumour state, prime, and support T cell-mediated anti-tumour immunity." (PMID 36161514, 2023). "The cGAS-STING signaling pathway is an important cytosolic DNA sensing pathway in vivo, which induces the expression of type I IFNs and affects the immune response of the body, and plays an important role in regulating pathogen infection, tumor immunity,and autoimmune diseases." (PMID 37667279, 2023). "However, the expression of cGAS-STING in tumor cells did not have a significant impact on patient OS in every stage." (PMID 37345163, 2023). "Chronic activation of the STING pathway induced by chromosomal instability (CIN) can promote downstream changes in cell signal transduction, thereby inhibiting highly effective anti-tumor immunity, which is one of the reasons why the cGAS-STING pathway in tumor cells does not work “normally”." (PMID 37920470, 2023). "Thus, there is a significant need to discover methods to activate tumor-intrinsic Type I IFN signaling in a manner that is independent of the cGAS/STING pathway." (PMID 36918588, 2023). "In addition, low levels of the cGAS-STING pathway are linked to a poor prognosis in various tumor types, and established tumor cell lines do not usually exhibit this pathway, indicating that the cGAS-STING pathway plays a role in preventing tumor progression." (PMID 35626108, 2022). "The cyclic GMP-AMP synthase (cGAS)-stimulator of interferon genes (STING) axis is an emerging immunotherapy target, with the resulting type I interferons and transcription factors acting at several levels in both tumor and immune cells for the generation of adaptive T cell responses." (PMID 36559204, 2022). "As the main activator of the antitumor immune response, the cGAS-STING pathway has been extensively studied in tumors with CIN/aneuploidy; therefore, successfully established tumors must evolve ways to avoid its activation or hijack its activation for tumor progression." (PMID 36003402, 2022). "Thus, activation of cGAS-STING, through mtDNA and/or dsDNA, in cancer cells may serve as a checkpoint to the initial progression of neoplasm by the secretion of Type 1 IFNs inflammatory genes." (PMID 36139387, 2022). "Activation of the cGAS-STING pathway can promote the maturation of antigen-presenting cells (APCs), induce the generation of cytokines and the production of CD8+ T cells against tumor antigens, and, at last, reshape the tumor microenvironment and enhance the anti-tumor immune response." (PMID 35889509, 2022). "DNA damaged from ageing, aberrant DNA leakage, and oxidative stress can accumulate in the cytoplasm of tumor cells, which activates two of the main components of DNA sensor machinery including stimulator of interferon genes (STING) and cyclic GMP–AMP synthase (cGAS) proteins." (PMID 35501802, 2022). "The cGAS-STING signaling pathway has a critical role in stimulating or enhancing innate and adaptive immunity through cytokines such as type I IFN, promoting the maturation and production of immune cells such as T cells, DCs, and NK cells to trigger effective anti-tumor immune effects." (PMID 35889509, 2022). "Hence, differential activation of the cGAS-STING pathway between normal and tumor cells might play a role in the FLASH effect regarding tumor control and sparing tissue from injuries such as fibrosis." (PMID 36291585, 2022). "DDRi-induced immune stimulation primarily occurs via the cGAS/STING pathway, but also occurs through signal transducer and activator of transcription 1 (STAT1) pathway activation and direct activation of immune cells including T cells, NK cells, and anti-tumor macrophages." (PMID 36276148, 2022).
tumor (continued). "In addition, DNA damage-mediated activation of the cGAS-independent non-canonical STING signaling primarily activates NF-kB and promotes IL-6 production, which is associated with pro-tumor response." (PMID 36353640, 2022). "Taken together, these studies paint a picture wherein cGAS may have functions unrelated to its role in STING signaling, and future studies will be needed to more clearly establish the roles that cGAS plays in tumor development and drug responses." (PMID 35602594, 2022). "Although the activation of the cGAS-STING signaling pathway has been tested as a potential cancer immunotherapy (see Therapeutic Strategies in Tumor Immunotherapy), the potential negative tumorigenic effects of overactivation of the cGAS signaling cannot be ignored." (PMID 35185917, 2022). "Together, these findings show the relevance of IFN signaling in suppressing tumor growth in TNBCs and underscore the critical role of MYC in suppressing the IFN response via direct inhibition of immunomodulatory factors downstream and in parallel of cGAS/STING signaling." (PMID 36323660, 2022). "Meq has been reported to have several functions, including inhibition of the cGAS–STING pathway, interaction with tumor suppressors, and transcriptional regulation, and deletion in the transactivation domain may reduce some of these protein functions or other unknown functions." (PMID 35215975, 2022). "In addition, Sex-determining region Y-related high-mobility group box 2 (SOX2) was found to occupy the cGAS promoter and repress its transcription, then dampen cGAS/STING signaling and ultimately inhibit ionizing radiation-induced anti-tumor immune responses in NSCLC45." (PMID 35978045, 2022). "Similarly, tumor DNA and tumor-derived cGAMP might act as stimuli for IFN-β production in endothelial cells via the signaling cascade involved in the cGAS-STING pathway." (PMID 35292881, 2022). "Consistent with this, IFNAR1 must be expressed by hematopoietic cells (including DCs) but not cancer cells to drive anti-tumor responses elicited by RT, establishing a pivotal role of the cGAS–STING–IFN-I–IFNAR1 axis in DCs in dictating therapeutic effects of RT." (PMID 34830176, 2021). "Beyond tumor cell-intrinsic genomic instability and CIN, exogenous DNA-damaging stimuli (e.g., radiation, cisplatin, etoposide and PARP inhibitors) and are able to increase the generation of cytosolic DNA and RNA, thus engaging either the cGAS–STING or RIG-I signaling pathways." (PMID 34884568, 2021). "Based on the anti-tumor immune response we observed in a previous study, we hypothesized that the PARP inhibitors could induce immune regulation through the activation of the cGAS/STING innate immune pathway." (PMID 34620163, 2021). "Interestingly, tumor and immune cells can communicate through the transfer of cGAMP and sEVs, demonstrating that cGAS expression by host immune cells is not necessarily required, while STING is." (PMID 34079557, 2021). "For example, tumor cells that express the ectonucleotidase ENPP1 degrade extracellular cGAMP, whose breakdown products can be further metabolized to adenosine, an immunosuppressive metabolite, toggling the cGAS-STING pathway from immunostimulatory to immunosuppressive." (PMID 34572943, 2021). "How these cells tolerate constitutive cGAS-STING activation without eliciting an anti-tumour immune response appears to hinge on the IFN dependent and independent activities of STING, which are engaged by the canonical and non-canonical pathways of NF-κB respectively." (PMID 33731858, 2021). "Therefore, how to utilize the anti-tumor effect of cGAS-STING without promoting metastasis is worthy of further research." (PMID 34207286, 2021). "Additionally, the cGAS-STING pathway was not activated by dsDNA in MB49 cells, but responded to the direct stimulus of cGAMP suggesting that cGAS is not functional in this tumor cell line." (PMID 34341449, 2021).
tumor (continued). "It has been proposed that tumor grade and origin may account for these differential outcomes following cGAS-STING stimulation, calling for stratification strategies to identify patients that would benefit from cGAS-STING targeting immunotherapies." (PMID 33981307, 2021). "While the number of neoantigens in a given tumor could not be easily manipulated, factors such cGAS/STING could be activated by external agents." (PMID 32566127, 2020). "In addition, we also found enrichment in the cGAS-STING cytosolic DNA-sensing pathway, and decreased expression of the TGF-β signalling pathway in the top quartile, which is concordant with previous studies on the tumour immune microenvironment 40–42." (PMID 33353943, 2020). "However, cGAS-knockout mice were not prone to spontaneous tumour development, supporting the fact that various tumour-suppressing pathways are able to prevent tumorigenesis." (PMID 33081170, 2020). "Thus, blockage of cGAS–STING axis both in stromal cells and tumor cells could be a potential anti-metastasis therapy." (PMID 32382015, 2020). "Besides, cGAS-STING pathway agonists can also increase antigen-presenting molecules such as Tap1, Tap2, and MHC-I with IFN upregulation, which may enhance the tumor immune surveillance." (PMID 32571374, 2020). "cGAS was dispensable in host cells but not cancer cells for optimal antitumor responses, suggesting tumor-derived cGAMP downstream of dsDNA sensing may be mediating activation of innate immune cells rather than dsDNA itself." (PMID 33238631, 2020). "In addition to being a driver of tumor evolution, recent evidence demonstrates CIN to be the central node of the crosstalk between a tumor and its surrounding microenvironment, as mediated by the cGAS-STING pathway." (PMID 31658669, 2019). "In addition, the cGAS-STING pathway is also believed to be involved in antitumour adaptive immunity, as activation of STING has been found to provoke a (CD8) T-cell response against the tumour in multiple instances." (PMID 31114634, 2019). "Activation of cGAS-STING signaling has also been recognized to mediate systemic tumor rejection by combined RT and checkpoint blockade given that knockdown of cGAS and STING in cancer cells abrogated priming of CD8+ T-cells in tumor-draining sites and infiltration of abscopal tumors by CD8+ T-cells." (PMID 29866197, 2018). "However, our data unequivocally demonstrate that the abscopal effect is abrogated when cancer cells in the irradiated tumour do not express cGAS/STING or overexpress Trex1, which preclude cancer cell-intrinsic activation of IFN-I pathway." (PMID 28598415, 2017). "Thus, as opposed to the well-known anti-tumour effects of type I interferons, sustained cGAS/STING pathway stimulation in aneuploid tumour cells leads to pro-inflammatory responses manifested by signalling molecules that act as tumour growth or invasion-promoting factors." (PMID 41188872, 2025). "Furthermore, mtDNA release from senescent cells enhances immunosuppression through the cGAS-STING pathway in myeloid-derived suppressor cells, suggesting that mitochondrial stress inducers may synergize with immunotherapy by remodeling the tumor immune landscape." (PMID 41282600, 2025). "Therefore, the activation of cGAS‐STING mediated by a CDH11 inhibitor offers specific advantages, as it selectively targets tumor tissue when administered systemically, eliciting an antitumor immune response within the tumor microenvironment, while minimizing the side effects on normal tissue." (PMID 39739317, 2025). "However, one of the drawbacks of using bulk transcriptomic data is that expression of cGAS-STING pathway components may reflect immune cell infiltration, rather than intrinsic cGAS-STING signaling in tumor cells." (PMID 38167507, 2024). "Additionally, other studies have shown that cGAS/STING may not entirely be an impediment to tumour growth." (PMID 39682099, 2024).